HNF4A (hepatocyte nuclear factor 4 alpha)
Diseases named in the same sentence as HNF4A in open-access papers (continued):
Sharing a sentence is not in itself a finding about the gene and the disease.
diabetes (continued). "The identification of several regulatory elements within the HNF4A 3′UTR justifies the analysis of the 3′UTR sequence to explore the dysfunction of HNF4α in diabetes and RCC." (PMID 22140441, 2011). "The interdependent function of Hnf1α and Hnf4α is also relevant to our understanding of how haploinsufficiency of HNF1A and HNF4A leads to β-cell dysfunction and diabetes." (PMID 20523905, 2010). "Our study predicts a common islet transcriptome defect in the pathophysiology of HNF1A and HNF4A diabetes." (PMID 20523905, 2010). "Surprisingly, HNF4A Pro437Ser is associated with a halved risk of T2D and reduced risk of diabetes-related complications but increased non-HDL cholesterol." (PMID 42238389, 2026). "This case highlights the importance of early recognition of monogenic diabetes in pregnancy, the potential utility of noninvasive prenatal testing, and the observation of persistent hyperinsulinemia beyond the neonatal period in HNF4A-related diabetes." (PMID 42064724, 2026). "Here, we describe a novel splicing variant in the HNF4A gene (c.319+1G>A) identified in a 15-year-old girl with non-ketoacidotic diabetes and a family history of diabetes." (PMID 40486195, 2025). "We also report a subject with a dual molecular diagnosis, BO-133, who had chronic kidney disease (stage IV at 78 years) with multiple bilateral cysts and diabetes mellitus: he had a frameshift variant in IFT140, but he was also found to have a whole gene deletion of HNF4A associated to MODY type 1." (PMID 40428294, 2025). "With the available data, we can only provide assessment of the evidence in HNF1A-diabetes although combined cohorts suggest results may be similar in HNF4A-diabetes." (PMID 39025920, 2024). "While five studies included both HNF1A-diabetes and HNF4A-diabetes, only three studies (16 individuals) had HNF4A-diabetes data that could be extracted." (PMID 39025920, 2024). "What is the optimal glucose-lowering therapy in HNF1A-diabetes and HNF4A-diabetes?" (PMID 39025920, 2024). "Clearly, more treatment studies are required in HNF4A-diabetes." (PMID 39025920, 2024). "Interestingly, the phenotype is shared with certain HNF4A (MODY1) and HNF1A (MODY4) mutations that cause hyperinsulinaemia at birth before evolving to decreased insulin secretion and diabetes in later life." (PMID 38366195, 2024). "Clinically, such patients usually present with diabetes like patients with HNF1A or HNF4A MODY." (PMID 39408828, 2024). "Youth in the TODAY study who were subsequently found to have HNF4A Maturity Onset Diabetes of the Young (MODY) were more likely to experience glycemic failure on metformin, a finding that was not surprising given their expected preferential response to sulfonylureas." (PMID 38590442, 2023). "For example, previous studies had estimated the penetrance of HNF4A rs137853336 (chr20:43042354C>T, p.Arg114Trp) to be up to 75% by age 40 years from a large Maturity Onset Diabetes of the Young cohort, but data from the UK Biobank estimated penetrance to be <10%." (PMID 37733810, 2023). "HNF4A, hepatocyte nuclear factor 4 alpha, might influence gluconeogenesis, diabetes, and lipid homeostasis." (PMID 37089789, 2023). "Given the absence of personal or family diabetes history, the HNF4A variant was reassessed and found to encode an alternative transcript with poor expression and activity levels, hence downgraded on expert advice from 'likely pathogenic' to 'likely benign'." (PMID 37664540, 2023). "As a result, excess vitamin A may contribute to dyslipidemia, diabetes, and metabolic syndrome, abnormalities for which HNF4α has been shown by others to be a significant factor." (PMID 37239961, 2023). "Hepatic Hnf4α expression is markedly reduced in diabetes, obesity, and NASH." (PMID 37727633, 2023).
diabetes (continued). "The use of 8 simple clinical features in the logistic regression model based MODY risk calculator distinguished the 3 common monogenic diabetes subtypes GCK, HNF1A, HNF4A collectively from Type 1 diabetes or Type 2 diabetes with a c-statistic of 0.98 and 0.95 respectively." (PMID 37794142, 2023). "Altered PDX1 and Hnf4-α function in humans has been associated with Maturity Onset Diabetes of the Young, a non-obese form of diabetes that can be mistaken for type 1 diabetes." (PMID 38348016, 2023). "Alternatively, the term “monogenic diabetes” followed by “subtype gene name” eg: monogenic diabetes subtype HNF4A may be used." (PMID 37794142, 2023). "Previous studies found that complete deletion of HNF4A in mice leads to early embryonic death, and specific deletion of HNF4A in mouse pancreatic β cells does not cause diabetes phenotype, despite impaired glucose-stimulated insulin secretion (GSIS)." (PMID 37711893, 2023). "Due to the marked family history for diabetes, a genetic investigation in the suspicion of MD was initially performed, using Sanger sequencing for HNF4A-, HNF1A-, and GCK-MODY, but no mutations were found." (PMID 36294752, 2022). "The benign trajectory of diabetes due to pathogenic GCK mutations, and the sulfonylurea-hyperresponsiveness conferred by activating KCNJ11 or ABCC8 mutations, or loss-of-function HNF1A or HNF4A mutations, often decisively guide clinical management." (PMID 35618782, 2022). "Our results thus reveal an important role of the hepatic let-7/TET3/HNF4α axis in mediating the therapeutic effects of metformin and suggest that targeting this axis may be a potential therapeutic for diabetes." (PMID 35344434, 2022). "We show that diabetes risk is substantially lower in clinically unselected settings for HNF1A/HNF4A-MODY but not for GCK-MODY." (PMID 36257325, 2022). "Our mutational analysis of only GCK, HNF4α, HNF1α, and HNF1β genes is not sufficient to strictly confirm the susceptibility mutation in patients with an onset of diabetes at an early age." (PMID 34746319, 2021). "These novel variants were shown to cosegregate with diabetes in additional family members, except for HNF4A c.68delG, because DNA from relatives was not available for testing." (PMID 31968686, 2020). "Increased insulin secretion in neonates and decreased insulin secretion in later life might explain the hypoglycemia and diabetes at various stages of the disease, but the mechanism of the differential aspects of the HNF4A defect on β-cell function is unclear." (PMID 30005691, 2018). "Prompt transfer to sulfonylureas, enabling optimal glycaemic control soon after diabetes diagnosis, may reduce the risk of future complications in those with HNF1A/HNF4A-MODY, as seen with type 1 and type 2 diabetes." (PMID 30229274, 2018). "Common variants in the monogenic diabetes genes HNF4A and WFS1, and a low-frequency variant in the HNF1A gene have also been associated with risk for T2D, highlighting the genetic overlap between monogenic diabetes and T2D." (PMID 29207974, 2017). "We did not detect a significant association between missense mutations in genes such as HNF1A and HNF4A, which are frequently mutated in early onset diabetes, likely due to the fact that not all missense mutations in these genes are pathogenic." (PMID 29207974, 2017). "Moreover, when overlaying with other canonical pathways in NASH, HNF4A and HNF1A are linked with to hepatic cholestasis, diabetes and FXR/RXR activation." (PMID 29216278, 2017). "In this study, we demonstrate that, with the experimental set-up described, insulin+, MAFA+, NKX6.1+ S7 cells can be generated in vitro from hiPSCs regardless of HNF4A mutation carrier status or diabetes status." (PMID 28684784, 2017). "Diabetes caused by HNF1A and HNF4A mutations is classically responsive to sulphonylurea treatment." (PMID 27330718, 2016).
diabetes (continued). "We had one subject with negative diabetes antibodies and a preserved C‐peptide who was found to have a mutation in HNF4A despite having no family history of diabetes." (PMID 26059258, 2016). "A good candidate among these common regulatory genes is Hepatocyte Nuclear Factor 4α (HNF4α, NR2A1, gene symbol HNF4A), a member of the nuclear receptor superfamily, essential for liver homeostasis and linked to several diseases including diabetes, hemophilia, atherosclerosis and hepatitis." (PMID 27135744, 2016). "Clinical studies have shown normal insulin sensitivity, but reduced glucose-stimulated insulin secretion in subjects with pre-diabetes with HNF-4A MODY, suggesting that pancreatic β-cell dysfunction rather than insulin resistance is the primary defect in this disorder." (PMID 24299156, 2014). "The next stage in this work will be to explore if these mutations influence the interaction between HNF4A and TAF4, and if they do, whether these changes contribute to this form of diabetes." (PMID 25209997, 2014). "MEDICA analogs have previously been reported to ameliorate T2D in animal models, and to mimic (n-3) PUFA activity in suppressing HNF-4α transcriptional activity, prompting our interest in probing their efficacy in preventing the development of diabetes-promoted CRC, as compared with fat-1." (PMID 25375205, 2014). "Diabetes in Cocker Spaniels showed an association with three SNPs from three different genes: MTTL1 (rs24305581), PAX4 (rs22302353) and INS (rs22686871) and in the miniature Dachshund there was a single association with HNF4A (rs8804236)." (PMID 26401325, 2014). "Other studies have identified high-sensitivityC-reactive protein (hsCRP), a known HNF1A target gene to be reduced in serum levels of subjects with HNF1A-MODY, compared to other forms of diabetes such as type 1 diabetes, type 2 diabetes, HNF4A-MODY, and glucokinase-MODY." (PMID 23803251, 2013). "Unlike, HNF1A and HNF4A monogenic diabetes, pancreatic atrophy is common in those with HNF1B mutations, therefore carriers do not display the same sensitivity to SU therapy and often require insulin therapy." (PMID 23766565, 2013). "Although it is not entirely clear how HNF4α protects against diabetes, it has been reported that mutations in HNF4α can lead to early death of pancreatic beta-cells resulting in pancreatic dysfunction and a subsequent decrease in insulin production." (PMID 22511885, 2012). "HNF4A regulates a common network of genes in liver and pancreas that when dysregulated may contribute to development of diabetes mellitus." (PMID 22719926, 2012). "Interestingly, like HNF4A, LPL is also suggested to be a diabetes susceptibility gene by human studies." (PMID 21689475, 2011). "Additionally, inconditional HNF4α knockout mice β-cell function wasimpaired upon glucose-stimulated insulin secretion whereasHNF1α knockout mice develop diabetes." (PMID 19252740, 2009). "Hereditary forms of diabetes also include rare monogenic variants such as MODY (Maturity-Onset Diabetes of the Young), which follows an autosomal dominant inheritance pattern caused by specific mutations in genes such as HNF4A, GCK, HNF1A, HNF1B, PDX1, and NEUROD1." (PMID 40647303, 2025). "The most striking features of HNF1α-/HNF4α-MODY are that they result in a reduced insulin secretory response to glucose but marked sensitivity to low-dose sulfonylureas and cause progressive pancreatic β-cell dysfunction and increasing hyperglycemia that leads to diabetes in early adult life." (PMID 34746319, 2021). "We expected there to be a small number of individuals in UKB with monogenic subtypes of diabetes, and we found two pathogenic variants that were associated with appropriate traits in UKB; we were thus able to lower the previous penetrance estimate for a pathogenic variant in HNF4A." (PMID 30665703, 2019).
diabetes (continued). "However, in MODY genes such as HNF1A and HNF4A, not all missense mutations increase the risk for diabetes and, therefore, it is challenging to ascribe pathogenicity to a novel missense mutation based on predictions made by bioinformatics tools." (PMID 29207974, 2017). "Regardless of the HNF4A mutation and diabetes disease status, the S7 populations were characterized by a mix of different stages of progenitor cells, including mixed islet cell populations, as well as cells expressing different hormone combinations (including bihormonal cells)." (PMID 28684784, 2017). "Functional analysis demonstrated that the HNF4A gene mutation T130I causes reduced expression in HeLa cells and thus affects protein function, whereas the HNF1A polymorphisms p.I27L and p.S487N may be associated with the age of diagnosis of diabetes." (PMID 26981542, 2016). "In addition, the prominence of the HNF-4A gene in the networks for E-PC2 and F-PC2 suggest that polymorphisms in this gene could influence asthma in addition to their known role in diabetes susceptibility." (PMID 25643280, 2015). "Whereas diabetes causing mutations are well known, there are no HNF4A mutations found in RCC." (PMID 22140441, 2011). "Our prediction model focuses on detecting common MODY subtypes (GCK‐, HNF1A‐, HNF4A‐ and HNF1B‐MODY), which account for over 80% of monogenic diabetes reported in Chinese." (PMID 40966384, 2025). "MD subtypes are many but most patients bear defects in four of the Maturity Onset Diabetes of the Young (MODY) genes: GCK, HNF1A, HNF4A, HNF1B." (PMID 40244428, 2025). "In a multicenter study, including 169 pediatric patients with monogenic diabetes, GCK-MODY was identified as the most common subtype, accounting for 59.2% of cases, whereas HNF1A-MODY and HNF4A-MODY were detected in 18.3% and 1.2% of patients, respectively." (PMID 41367630, 2025). "Most types of monogenic diabetes have reduced penetrance and variable expressivity, including HNF1A, HNF4A, and RFX6, which is considered a candidate gene for MODY, emphasizing the role of environment and genetic factors." (PMID 40148250, 2025). "Similar to HNF1A-MODY, patients with HNF4A-MODY typically exhibit signs and symptoms of diabetes that develop gradually during childhood or young adulthood." (PMID 40149950, 2025). "Based on Condel functionality scores and centrality positions in genetic interaction networks, two prominent candidates in diabetes mellitus and maturity-onset diabetes of the young (MODY)—HNF1A rs2464195 and HNF4A rs147638455—were identified." (PMID 41376825, 2025). "Firth logistic regression models were developed on data from 3541 paediatric patients from the Swedish ‘Better Diabetes Diagnosis’ (BDD) population study (n = 46 (1.3%) MODY (HNF1A, HNF4A, GCK))." (PMID 38719926, 2024). "Our data provides a valuable resource to investigate the downstream targets of HNF4A and HNF1A, to identify molecular mechanisms in normal beta cells and hepatic cells as well as their dysfunction in the context of diabetes." (PMID 38909044, 2024). "Furthermore, in a study involving 922 families referred for MODY testing, spontaneous de novo mutations affecting the GCK, HNF1A, or HNF4A genes were reported in 11 of 150 individuals who did not have autosomal dominant inheritance of diabetes or a multigenerational family history of hyperglycemia." (PMID 39902162, 2024). "What is the optimal glucose-lowering therapy in the three commonest subtypes of autosomal dominant familial diabetes also known as Maturity Onset Diabetes of the Young (MODY): GCK-related hyperglycemia, HNF1A-diabetes, and HNF4A-diabetes?" (PMID 39025920, 2024). "The genetic content of the monogenic diabetes NGS panel used is recommended to include at least the 5 common diagnoses (GCK, HNF1A, HNF1B, HNF4A, and m.3243A>G)." (PMID 37033247, 2023).
diabetes (continued). "This indicates excellent discrimination between Type 1 diabetes or Type 2 diabetes and the 3 common monogenic diabetes subtypes GCK, HNF1A, HNF4A collectively, as well as when comparing Type 1 and Type 2 diabetes with HNF1A/4A and GCK etiologies separately." (PMID 37794142, 2023). "Compared with type 2 diabetes mellitus (T2DM), HNF4A-MODY occurs at younger ages with lower hemoglobin A1c, body mass index (BMI), triglyceride levels, and a similar risk of microvascular complications." (PMID 37711893, 2023). "Moreover, the exclusive presence of HNF4A expression in adipocytes derived from d-hASCs, but not in the hASCs group, highlights its strong association with the “lipid metabolism” in one human research related to diabetes." (PMID 37445596, 2023). "The most common forms of monogenic diabetes, HNF1A, HNF4A, and GCK etiologies, are dominantly inherited, and the vertical transmission of diabetes or hyperglycemia is often evident in the pedigree." (PMID 37794142, 2023). "With this unicentric cohort study, we intended to evaluate the accuracy of MPC for the screening of monogenic diabetes subtypes GCK, HNF1A and HNF4A MODY." (PMID 35822264, 2022). "Several genes were found to be enriched, however hepatocyte nuclear factor 4 alpha (HNF4A) and paired box 4 (PAX4) were found to be strongly related to the diabetes onset pathway." (PMID 36037214, 2022). "Based on text mining, most of the highly common diabetes-related genes in the literature were correlated with glucagon and AMPK signaling pathways such as HNF4A, PCK2, and SIRT1, which were among the most interactive genes in the PPI analysis." (PMID 36360783, 2022). "HNF4α-related diseases include non-alcoholic fatty liver disease (NAFLD), obesity, hypertension, hyperlipidemia, metabolic syndrome and diabetes mellitus." (PMID 36249028, 2022). "Previous studies suggested that MODY probably accounts for 1–5% of overall diagnosed diabetes, with the most commonly reported subtypes as GCK-MODY (MODY2), HNF1A-MODY (MODY3), and HNF4A-MODY (MODY1)." (PMID 35921062, 2022). "In our whole study, 16/297 (5.4%) of patients had monogenic diabetes due to either a partial or whole gene deletion (14 HNF1B, 1 HNF1A and 1 HNF4A)." (PMID 34789499, 2022). "Pubmed was searched for publications on the subject by employing search terms: MODY, Maturity Onset Diabetes of the Young, monogenic diabetes, HNF1A, HNF-1 alpha, GCK, glucokinase, HNF1B, HNF-1 beta, HNF4A, HNF-4 alpha, biomarkers." (PMID 32528556, 2020). "HNF4A-MODY is characterized by fetal macrosomia, transient neonatal hyperinsulinemic hypoglycemia, progressive development of hyperglycemia, and onset of diabetes mellitus in late adolescence or by 25 years of age." (PMID 33292863, 2020). "We also assessed the combined effect of diabetes duration and HbA1c at genetic diagnosis on the ability to achieve good glycaemic control with diet/sulfonylurea alone in individuals with HNF1A/HNF4A-MODY." (PMID 30229274, 2018). "In those with HNF1A/HNF4A-MODY, a shorter diabetes duration, lower HbA1c and lower BMI at genetic diagnosis predicted successful treatment with sulfonylurea/diet alone, supporting the need for early genetic diagnosis and treatment change." (PMID 30229274, 2018). "A shorter duration of diabetes, lower HbA1c level and lower BMI at genetic diagnosis predicted successful treatment with sulfonylurea/diet alone in participants with HNF1A/HNF4A-MODY, supporting the need for early genetic diagnosis and treatment change." (PMID 30229274, 2018). "In the future, non‐invasive pre‐natal genetic testing will enable personalized management of HNF4A MODY and KATP neonatal diabetes pregnancies." (PMID 28556992, 2017). "Furthermore, also regardless of HNF4A mutation carrier status or diabetes status, the S7 cells displayed the same GSIS kinetics, the same ultrastructural features and the same levels of proteomics-based protein markers of a mature β-cell, including INS, PDX1, NKX6.1, MAFA, GLUT2, UCN3 and others." (PMID 28684784, 2017).